CCK (cholecystokinin)
Diseases named in the same sentence as CCK in open-access papers (continued):
Sharing a sentence is not in itself a finding about the gene and the disease.
Anxiety (continued). "Potential safety concerns from treatment with CCK or CCK analogues are pancreatitis mediated by pancreatic and/or vagal CCK-1 receptors, and anxiety mediated by central CCK-2 receptors." (PMID 31175319, 2020). "Taken together, we have demonstrated that OLETF rats exhibit region-specific area reductions and increased CCK positive neurons in the emotion-related brain regions and increased anxiety-like behavior in the early stage of type 2 diabetes." (PMID 32938363, 2020). "Behavioral researches have documented the prominent function of CCK in nocebo hyperalgesia through anticipatory anxiety mechanisms." (PMID 33133178, 2020). "Several studies investigated the direct role of CCK in modulating anxiety and stress responses in human subjects." (PMID 32824625, 2020). "Our data suggest an association between imbalances in the brain area and the composition of CCK positive neurons in the corticolimbic system, and anxiety-like behavior in OLETF rats." (PMID 32938363, 2020). "The most important neuropeptides that play a role in the modulation of stress-related behaviors and anxiety are cholecystokinin (CCK), oxytocin (OXT), substance P, neuropeptide Y, galanin, pituitary adenylate activator polypeptide (PACAP), ghrelin, and leptin." (PMID 32824625, 2020). "Here, OLETF rats exhibited the increased densities of CCK positive neurons in the LA, BLA, CA2, and PL; and that in the CA2 was associated with increased anxiety-like behavior." (PMID 32938363, 2020). "In the present study, we have demonstrated that OLETF rats exhibit region-specific area reductions and increased CCK positive neurons in emotion-related brain regions and increased anxiety-like behavior in the early stage of type 2 diabetes." (PMID 32938363, 2020). "To exclude the possibility that anxiety influenced the contextual fear memory in CCK-GABA/hM3Dq+ mice, we next measured contextual discrimination." (PMID 30834305, 2019). "The impact of anxiety and the anxiety-related neurotransmitter cholecystokinin on nocebo effects in pain has already been established." (PMID 31379627, 2019). "Social recognition is constrained by anxiety, but also involves memory processes and is regulated by the hippocampus, a brain region where CCK-GABA neurons are relatively abundant." (PMID 30834305, 2019). "Behavioral data revealed that the activation of CCK-GABA neurons enhances memory and cognitive performance in CCK-GABA/hM3Dq+ mice with minimal effects on anxiety." (PMID 30834305, 2019). "This anxiety-inducing effect of CCK has also been observed in pharmacological provocation studies following intracerebroventricular injection of CCK-8 in rats that reduced exploratory behavior in the light/dark paradigm." (PMID 30210455, 2018). "PD patients are also susceptible to the induction of panic attacks not only by CO2 but also by systemic administration of a variety of agents, such as lactate, cholecystokinin, and norepinephrine." (PMID 30194289, 2018). "CCKBR is a G protein-coupled receptor for gastrin and cholecystokinin (CCK), which primarily regulates anxiety, feeding, and locomotion in the brain." (PMID 29770110, 2018). "The brain reward circuitry as well as anxiety and subsequent activation of both the cholecystokinin (CCK) and hypothalamic-pituitary-adrenal (HPA) systems seem crucial facilitators of these effects." (PMID 27090420, 2016). "Both the PARV interneurons and the CCK interneurons appear to reduce fear and anxiety, while the SST interneurons appear to increase fear." (PMID 27766068, 2016). "An important role for CCK-GABA neurons in anxiety and fear has been shown, though this function has been largely attributed to a modest population of neurons in the amygdala." (PMID 26441554, 2015). "Further, CCK-GABA neurons target post-synaptic regions that are enriched with receptors involved in anxiety behaviors, namely CCK type B and α2 subunit-containing GABAA receptors." (PMID 26441554, 2015).
Anxiety (continued). "SST microinfusions in the amygdala produce anxiolytic- and antidepressant-like effects, likely through modulation of GABAA receptor signaling, whereas administration of CCK elicits anxiety-like behavioral responses." (PMID 24478650, 2014). "For example, the orexigenic neuropeptide NPY has been shown to exert anxiolytic effects and the anorexigenic peptide cholecystokinin (CCK) induces panic-like effects, impacting on general anxiety and stress-related behavior." (PMID 24009547, 2013). "The genes CCK, POMC, MCHR1, GABRA6, HTR2A and DRD2, which associated with heat score in at least one brain area, are known to modulate emotional states like anxiety and satiety or even sexual motivation." (PMID 21504592, 2011). "Gut microbes may modulate brain states by influencing the release of glucagon-like peptide, cholecystokinin, adrenocorticotropin-releasing factor, neuropeptides, and other factors, and may play a role in ameliorating anxiety and depressive symptoms." (PMID 40357036, 2025). "The increased anxiety in the CCK‐KO mice is paradoxical, because it is now well established that peripheral administration of exogenous CCK‐4 and CCK‐8 in a dose‐related manner induces panic attacks of anxiety in mammals, among which human subjects have been carefully studied." (PMID 40557463, 2025). "On top of the role of CCK in anxiety and panic disorders, it has now been suggested that CCK peptides may be promising drug candidates for the therapy of Alzheimer's and Parkinson's diseases." (PMID 40557463, 2025). "Cholecystokinin (CCK) is a peptide involved in anxiety and panic." (PMID 37585661, 2024). "The alteration of CCK and its receptors has been reported in substance addictions such as cocaine, methamphetamine, and alcohol, and the activation of CCK receptors has also been shown to modulate the mesolimbic reward system and anxiety behavior." (PMID 37962470, 2023). "Stress, fear, and anxiety are known to be controlled by CCK." (PMID 35707787, 2022). "Additionally, CCK plays important roles in neuromodulation in several brain circuits that regulate reward, anxiety, aggression and sexual behavior." (PMID 35286508, 2022). "Malnutrition-induced alterations in gut microbiota may increase the sensitivity to anxiety-inducing gastrointestinal hormones released during meals, one of which is cholecystokinin (CCK)." (PMID 35893544, 2022). "Activation of NTS CCK neurons that terminate in the PBN also induces anxiety-like behaviors." (PMID 35330845, 2022). "Moreover, the authors also discovered that the CCK role in anxiety and depression is far more complex." (PMID 36004833, 2022). "It was previously established that CCK neurons in the amygdala play an important role in modulating fear and anxiety like behaviors, yet the mechanisms of action of CCK in frontal cortical circuits remains unclear." (PMID 35800635, 2022). "CCK-expressing neuronal projections have been identified within the limbic system, the brainstem, and the cerebral cortex, areas known to overlap with neuronal pathways that are involved in the modulation of fear, anxiety, and aggression." (PMID 35286508, 2022). "Moreover, the CCKBR agonist CCK-tetrapeptide (CCK-4) induces acute panic attacks in healthy human subjects and patients with a panic disorder." (PMID 34779397, 2021). "There is also evidence to suggest that cholecystokinin may play a role in anxiety and panic disorders." (PMID 34367142, 2021). "In addition to CCK, however, it is now established that several other transmitter systems also are involved in the pathophysiology of panic attacks." (PMID 34577128, 2021). "We previously reported that 20-week-old Otsuka Long-Evans Tokushima fatty (OLETF) rats, a model of progressive type 2 diabetes, showed increased anxiety-like behavior and regional area reductions and increased cholecystokinin-positive neurons in the corticolimbic system." (PMID 34506507, 2021).
Anxiety (continued). "Furthermore, knockdown of CCK in the basolateral amygdala (BLA) decreased anxiety-like behavior in the elevated plus maze test." (PMID 34506507, 2021). "Interestingly, we found that 20-week-old OLETF rats exhibited increased numbers of CCK-positive neurons in the corticolimbic system, including the mPFC, amygdala, and hippocampus, which might be indicative of the neural mechanisms causing increased anxiety-like behavior." (PMID 34506507, 2021). "Whether a similar neuronal mechanism, from peripheral plasma CCK to anxiety centers in the brain (amygdala), exists also remains to be studied." (PMID 34577128, 2021). "Thus, the C-terminal tetrapeptide fragment of CCK (CCK-4) induces, by intravenous administration in a dose-related manner, panic attacks that are similar to the endogenous attacks in panic disorder patients." (PMID 34577128, 2021). "Cholecystokinin-4, another form of cholecystokinin, has been known to induce panic attacks." (PMID 32802040, 2020). "Collectively, these findings led us to hypothesize that OLETF rats may have imbalances in the brain areas and composition of CCK and PV expression in the limbic system related to increased anxiety-like behavior in the early stage of type 2 diabetes." (PMID 32938363, 2020). "To address this hypothesis, we investigated brain weight and areas, the densities of CCK and PV positive neurons in the limbic system, and anxiety-like behavior, and analyzed the relationships between these alterations." (PMID 32938363, 2020). "Notably, its mammalian homolog cholecystokinin (CCK) regulates aggression and anxiety and has been implicated in panic disorder." (PMID 33193727, 2020). "A primary mechanism of the nocebo effect is verbal-induced anxiety for perceived negative outcomes causing the release of cholecystokinin (CCK), thereby accentuating pain and sensation responses." (PMID 33467255, 2020). "We hypothesized that alterations of localized brain areas and cholecystokinin (CCK) and parvalbumin (PV) expression could induce anxiety-like behavior in type 2 diabetic Otsuka Long-Evans Tokushima fatty (OLETF) rats." (PMID 32938363, 2020). "CCK has been reported to be involved in anxiety-like behavior." (PMID 32938363, 2020). "Similarly, experimental CCK injections in the amygdala, hippocampus, mPFC, and the cerebral ventricle increase anxiety-like behavior through the activation of the CCK-2 receptor." (PMID 32938363, 2020). "These global factors will usually be endogenous compounds (acting in a hormonal or neuro-hormonal fashion) such as serotonin (controlling “stability”), endogenous BDZ ligands (controlling “trait anxiety”) and perhaps cholecystokinin (CCK) acting within the PAG (controlling “trait panic”)." (PMID 32524065, 2020). "One proposal is that endocannabinoids could inhibit CCK release in the BA and thereby oppose the peptide’s pro-fear/anxiety effects to enable extinction." (PMID 31636080, 2019). "After a 4 h fast, appetite perceptions, GI symptoms, state anxiety, and plasma acyl-ghrelin, cholecystokinin (CCK), peptide tyrosine tyrosine (PYY) and pancreatic polypeptide (PP) concentrations were assessed at baseline and in response to a mixed-nutrient test-meal (479 kcal)." (PMID 30597915, 2018). "Moreover, we also tested the CCK-SAP animals in an additional anxiety-relevant task, the open field test." (PMID 29872139, 2018). "In the behaving mouse, inhibition of TRPC4 and TRPC5 results in anxiolytic disinhibition of exploration in a CCK-anxiety model, decreased marble burying, increased activity in tests of antidepressant efficacy, and amelioration of hyper-fear memory in socially stressed mice." (PMID 29385160, 2018). "Cholecystokinin has well-known anxiogenic effects, at least in part via the amygdala and prefrontal cortex, and thus restored CB1 receptor expression in these neurons may reduce anxiety-like behavior via a reduction of cholecystokinin release." (PMID 28393261, 2017).
Anxiety (continued). "The role for CCK in the induction and persistence of anxiety and major depression is conspicuous." (PMID 22848639, 2012). "Consistent with this, anorexigenic peptides such as leptin and cholecystokinin have been reported to increase anxiety-like behavior, whereas the orexigenic peptide neuropeptide Y (an established target for ghrelin in the arcuate nucleus) reduces anxiety-like behavior." (PMID 23071554, 2012). "Therefore, we concluded that the effect of LY-288,513 on the acquisition of CPA is at least partially related to the CCK-opioid interaction and the role of CCK in anxiety by activating the CCK2 receptor." (PMID 22848639, 2012). "In vivo APA has also been shown to cleave cholecystokinin (CCK-8), which is widely distributed in the mammalian central nervous system and could be involved in pain perception, feeding, anxiety and memory." (PMID 20706583, 2010). "Hence, global KO of the CCK gene shows that mice have lost their memory and exhibit increased anxiety, in addition to peripheral disturbances of digestive and endocrine functions that also may interfere with memory functions." (PMID 40557463, 2025). "Likewise, the expression of Erbb4 is increased in CCK-SAP rats compared with control rats: mice with high anxiety phenotype display low levels of ErbB4 in the amygdala, and administration of its ligand neuregulin 1 is anxiolytic while enhancing GABAergic neurotransmission." (PMID 35965105, 2022). "Moreover, CCK knock-down in the BLA reduces anxiety-like behavior in the elevated plus maze test." (PMID 32938363, 2020). "The effects of CCK in anxiety could be a consequence of its activation of the HPA axis." (PMID 31271235, 2019). "Thus, we tested both SDV and CCK-SAP rats in the zero maze anxiety test." (PMID 29872139, 2018). "Collectively, the downregulation of CRYAB, CCK, and PLP1 appears to play a critical role in the cognitive impairment and anxiety-like behavior observed in anosmic mice in the present study." (PMID 40673140, 2025). "Abnormal expression of brain-gut peptides, like ghrelin, NPY, CCK, PYY, and GRP, in the peripheral and central systems can lead to depression, anxiety, gastrointestinal diseases, and metabolic disorders." (PMID 37511879, 2023). "For this, we infused the GABAA receptor antagonist bicuculline bilaterally (100 pmol in 0.2 μL per side) into the CeA of male CCK-SAP rats or their corresponding control rats and tested their anxiety-like behavior in the acoustic startle test." (PMID 35965105, 2022). "An increasing number of different neuropeptide systems (e.g., galanin, cholecystokinin, and NPY) have been shown to modulate fear and anxiety in rodents and humans." (PMID 34072275, 2021). "Contrary to CCK-positive neurons, chemogenetic inhibition of PV-positive neurons in the BLA increased anxiety-like behavior in the open-field and elevated plus maze tests." (PMID 34506507, 2021). "CCK-4 studies have unequivocally demonstrated that cerebral CCK-peptides and CCK2-receptors play a significant role in panic attacks." (PMID 34577128, 2021). "In addition, CCK acts as a neurotransmitter in the CNS and may reduce food intake by the activation of central CCKARs, a phenomenon highly relevant for integrating metabolic balance with fear and anxiety‐related behaviors." (PMID 31271235, 2019). "It has been argued that CCK-GABA neurons are ideally suited for the regulation of mood, anxiety and fear." (PMID 26441554, 2015). "An interplay of CCK signaling and NMDA receptor has been reported in several contexts, including food intake and anxiety behavior; furthermore, CGE-derived CCK interneurons have a distinct NMDA subunit composition." (PMID 25875176, 2015). "Several lines of evidence suggest that CCK modulates glutamate-GABA mechanisms by acting on CCK-2 receptors, and resulting in subsequent disinhibition of the central amygdaloid nucleus and anxiety or panic-like behavior." (PMID 22848639, 2012).
Anxiety (continued). "We have identified a specific genetic signature of alterations in dopaminergic and CCK signaling indicating that the presence of alterations in both pathways modulates depressive-like, but not anxiety-like, behavior." (PMID 37881580, 2023). "The anxiety- and depression-related behaviors typically accompanying persisting hypersensitivity subsequently never developed in the mice given CCK-BR scFv." (PMID 37446213, 2023). "Noteworthy, cholecystokinin (CCK)‐immunoreactive circuits and CCK2 receptors within brainstem centers may play a role in anxiety responses." (PMID 33713315, 2021). "Several lines of evidence suggest that those neuropeptides, which are increased by hunger (NPY and AgRP), also reduce fear and anxiety, while others released upon refeeding and in particular during states of satiety are predominantly anxiogenic (α‐MSH, CRH, and CCK)." (PMID 31271235, 2019). "It has been hypothesized that CCK-GABA neurons are functionally specialized for the regulation of emotional behaviors such as mood, anxiety and fear." (PMID 30834305, 2019). "CNO treatment did not affect interaction time (p > 0.86), a finding which suggests that systemic activation of CCK-GABA cells does not affect sociability or anxiety." (PMID 30834305, 2019). "Together, these results suggest that CCK-GABA neuron activation does not affect locomotion or depression-like behavior but mildly increases anxiety-like behavior in CCK-GABA/hM3Dq+ mice." (PMID 30834305, 2019). "In another report, inhibition of GABA synthesis in CCK-expressing cells disrupted olfaction and locomotion but not recognition memory or anxiety." (PMID 30834305, 2019). "Additionally, the postsynaptic targets of CCK-GABA neurons are enriched with α2-containing GABAA receptors, which regulate anxiety behaviors and the effects of anxiolytic drugs." (PMID 30834305, 2019). "Results revealed no significant group differences in either SDV or CCK-SAP groups relative to controls in these anxiety-related tests." (PMID 29872139, 2018). "Interneurons also use neuropeptides, such as cholecystokinin (CCK) and neuropeptide Y (NPY), as co-transmitters that exert profound effects on fear, anxiety, learned helplessness behavior and stress response, and stress was found to affect their expression as well." (PMID 26793083, 2015). "CCK has been shown to participate in anxiety and stress- related behaviors which reflect the negative affect of morphine withdrawal and are the most important behavioral changes involved in CPA expression." (PMID 22848639, 2012). "Metabolic theories have also been quite popular suggesting that PD sufferers are more reactive to certain anxiety-inducing substances or conditions such as injections of lactic acid, elevated CO2 levels, caffeine, yohimbine, m-cholorophenylpiperazine, cholecystokinin (CCK), nicotine, and alcohol." (PMID 36793941, 2023). "CCK could interact with multiple neurotransmitters, such as DA, GABA, 5-HT, and endogenous opioids, to modulate the mesolimbic reward system, anxiety, and satiety, which are involved in positive and negative reinforcement processes of the development of dependence." (PMID 37962470, 2023). "A large literature has shown that various neuropeptides, including corticotropin-releasing factor (CRF), cholecystokinin (CCK), arginine vasopressin (AVP), oxytocin, orexin, neuropeptide Y (NPY), neuropeptide S (NPS), galanin, and neurokinins, such as substance P, affect anxiety-related behaviors." (PMID 36623804, 2023). "Since panic disorder is a rather common psychiatric condition, with a prevalence among women of 5% and 2% in men, you could argue that some involvement of the cerebral CCK-system in the pathogenesis of panic attacks should not come as a surprise." (PMID 34577128, 2021).